CPSF6 (cleavage and polyadenylation specific factor 6)
Description:
Component of the cleavage factor Im (CFIm) complex that functions as an activator of the pre-mRNA 3'-end cleavage and polyadenylation processing required for the maturation of pre-mRNA into functional mRNAs. CFIm contributes to the recruitment of multiprotein complexes on specific sequences on the pre-mRNA 3'-end, so called cleavage and polyadenylation signals (pA signals). Most pre-mRNAs contain multiple pA signals, resulting in alternative cleavage and polyadenylation (APA) producing mRNAs with variable 3'-end formation. The CFIm complex acts as a key regulator of cleavage and polyadenylation site choice during APA through its binding to 5'-UGUA-3' elements localized in the 3'-untranslated region (UTR) for a huge number of pre-mRNAs. CPSF6 enhances NUDT21/CPSF5 binding to 5'-UGUA-3' elements localized upstream of pA signals and promotes RNA looping, and hence activates directly the mRNA 3'-processing machinery. Plays a role in mRNA export. (Microbial infection) Binds HIV-1 capsid-nucleocapsid (HIV-1 CA-NC) complexes and might thereby promote the integration of the virus in the nucleus of dividing cells (in vitro).
Synonyms: CFIm68; CFIM; HPBRII-4; HPBRII-7; CFIM72
Tractability: Small molecule: a structure with a bound ligand is known. PROTAC: ubiquitination databases record sites on it; its protein half-life has been measured.
Gene: Protein-coding gene on chromosome 12 (69,239,543 to 69,279,829, forward strand). Ensembl gene ENSG00000111605.
Subcellular location: Nucleus; Nucleus, nucleoplasm; Nucleus speckle; Cytoplasm
Subcellular location (Human Protein Atlas): Nuclear speckles; Nucleoplasm
Pathways (Reactome):
Disease: Dengue Virus-Host Interactions; Signaling by FGFR1 in disease; Signaling by cytosolic FGFR1 fusion mutants
Metabolism of RNA: Processing of Intronless Pre-mRNAs; mRNA 3'-end processing; mRNA Polyadenylation
Gene expression (Transcription): RNA Polymerase II Transcription Termination
Gene Ontology:
Molecular function: exon-exon junction complex binding; mRNA binding; protein binding; ribosomal large subunit binding; RNA binding; nucleic acid binding
Biological process: co-transcriptional mRNA 3'-end processing, cleavage and polyadenylation pathway; mRNA 3'-end processing; mRNA alternative polyadenylation; mRNA processing; positive regulation of RNA export from nucleus; protein heterotetramerization; protein tetramerization
Cellular component: cytoplasm; interchromatin granule; membrane; mRNA cleavage and polyadenylation specificity factor complex; mRNA cleavage factor complex; nuclear speck; nucleoplasm; nucleus; paraspeckles; perichromatin fibrils; ribonucleoprotein complex
Genetic constraint (gnomAD): Loss-of-function variants: 7 observed, 42.93 expected, observed/expected ratio (o/e) 0.16, 90% interval 0.092 to 0.31. The upper end of that interval is the gene's LOEUF score, 0.31, which puts it in group 1 of 6, group 1 being the genes least tolerant of losing a copy. Missense variants: 382 observed, 671.39 expected, observed/expected ratio (o/e) 0.57, 90% interval 0.52 to 0.62. Synonymous variants: 226 observed, 228.8 expected, observed/expected ratio (o/e) 0.99, 90% interval 0.88 to 1.1.
Homologues: Orthologues: chimpanzee CPSF6 (100% identical), dog CPSF6 (100% identical), macaque CPSF6 (100% identical), pig CPSF6 (100% identical), rabbit CPSF6 (100% identical), guinea pig CPSF6 (99% identical), rat Cpsf6 (99% identical), mouse Cpsf6 (99% identical), tropical clawed frog cpsf6 (89% identical), zebrafish cpsf6 (84% identical), Drosophila melanogaster Cpsf6 (45% identical), Caenorhabditis elegans cfim-2 (29% identical). Paralogues in human: CPSF7 (44% identical).
Diseases named in the same sentence as CPSF6 in open-access papers:
CPSF6 is named in the same sentence as 41 diseases in open-access papers, as found by Europe PMC text mining. Sharing a sentence is not in itself a finding about the gene and the disease. The quoted sentences say what the papers report.
HIV-1 infection (54 papers, 2011 to 2026). The type species of lentivirus and the etiologic agent of acquired immunodeficiency syndrome (AIDS). "In contrast, loss of CPSF6 markedly reduced the efficacy of HIV-1 infection, by up to 9.8-fold, compared to the NTC reference in these primary cells." (PMID 34949807, 2022). "Cleavage and polyadenylation specific factor 6 (CPSF6), a member of serine/arginine-rich protein family, is implicated in HIV-1-infection and replication." (PMID 36446361, 2022). "Based on these data the conclusion was made that inhibition of HIV-1 infection by TRN-SR2 KD is caused by cytoplasmic localization of CPSF6 and subsequent hyperstabilization of the CA cone hence attributing an indirect role to TRN-SR2 in HIV-1 nuclear import." (PMID 34064404, 2021). "In fact, HIV-1 virions carrying CA mutation N74D that cannot interact with CPSF6 trigger innate sensors that induce an antiviral state against HIV-1 infection in macrophages." (PMID 31465518, 2019). "Altogether, these results imply that the effect of TNPO3-depletion on HIV-1 infection is in part linked to CPSF6." (PMID 22888429, 2012). "Thus, the antiviral effect of CPSF6 is active against virus carrying naturally occurring mutations in relevant targets of HIV-1 infection in vivo." (PMID 24415937, 2014). "While the role of endogenous CPSF6 protein in HIV-1 infection is unknown, the cytoplasmic CPSF6358 truncation variant potently restricts HIV-1." (PMID 24130490, 2013). "Contrary to CPSF6, the NES-CPSF6 variant potently block HIV-1 infection." (PMID 23622145, 2013). "Our study demonstrates that HIV-1 infection leverages the interaction between the viral capsid and CPSF6 to co-opt cellular processes, alter gene expression, and potentially contribute to viral pathogenesis." (PMID 41405390, 2026). "Overall, our study demonstrates that HIV-1 infection exerts control over cellular gene expression by leveraging the interaction between the viral capsid and CPSF6 to alter the subcellular localization of CPSF5 and CPSF6, impacting their functions." (PMID 41405390, 2026). "Overall, this study suggests that HIV-1 infection mimics the phenotype observed in CPSF6-KO cells, indicating that HIV-1 sequesters CPSF5 and CPSF6 in nuclear speckles to alter their function, representing a novel regulatory mechanism." (PMID 41405390, 2026). "To determine the contribution of CPSF6’s disordered domains to the formation of CPSF6 puncta upon HIV-1 infection, we correlated the binding of CPSF6 to the HIV-1 core with the formation of CPSF6 puncta." (PMID 41493399, 2026). "Formation of CPSF6 puncta upon HIV-1 infection hinges on two key events: the entry of the HIV-1 core into the nucleus and the binding of CPSF6 to the HIV-1 core." (PMID 41493399, 2026). "HIV-1 infection modulates the CFIm complex through direct interaction between the viral capsid and CPSF6, and these experiments suggest that the sequestration of CPSF6 to nuclear speckles by the viral capsid affects the cellular function of the CFIm complex." (PMID 41405390, 2026). "We and others have shown that HIV-1 infection triggers the translocation of CPSF6 to nuclear speckles." (PMID 41405390, 2026). "Due to the high efficiency of HIV-1 infection–induced CPSF5 and CPSF6 translocation to nuclear speckles in human A549 cells, we initially studied HIV-1-infection–induced changes in cellular expression in this cell line." (PMID 41405390, 2026). "Similar to the phenotype observed in CPSF6-KO cells, we observed that HIV-1 infection decreases CPSF5 protein expression levels." (PMID 41405390, 2026). "This study demonstrates that HIV-1 infection alters the cellular function of CPSF6, an essential regulator of alternative polyadenylation—a mechanism that controls 70% of gene expression." (PMID 41405390, 2026). "Our results suggest that HIV-1 infection affects APA through the interaction of viral capsid with CPSF6, resulting in the shortening of mRNA 3’UTRs, ultimately changing cellular protein expression levels." (PMID 41405390, 2026).
HIV-1 infection (continued). "We propose that HIV-1 infection alters cellular expression by modulating APA through the interaction of the viral capsid with CPSF6." (PMID 41405390, 2026). "Previously, we and others described that HIV-1 infection induces the translocation of both CPSF6 and CPSF5, a CFIm complex member that works together with CPSF6, to nuclear speckles." (PMID 41405390, 2026). "CPSF6 was first implicated in HIV-1 biology via a genetic screen for mouse-specific restriction factors, as mouse cells are refractory to HIV-1 infection." (PMID 40202316, 2025). "To better understand the role of CPSF6 in HIV-1 infection, we used CRISPR-Cas9 ribonucleoproteins (crRNPs) to knock-out CPSF6 in primary CD4+ T cells from 4 independent donors." (PMID 41385587, 2025). "This study highlights the importance of the NLS in CPSF6 to dictate nuclear import pathways that are congruent with functional HIV-1 infection." (PMID 39823525, 2025). "Despite these many roles in the viral lifecycle, reported HIV-1 infection phenotypes upon CPSF6 depletion vary widely by viral strain and cell type, including some conditions that result in an increase in viral infectivity." (PMID 41385587, 2025). "Collectively, these results suggest that the detrimental effect of disrupting the CPSF6–CA interaction on HIV-1 infection is short-lived, which is consistent with the notion that CPSF6’s effect on HIV-1 infection is both context and cell-type dependent." (PMID 40202316, 2025). "To test this, we first used the HT1080 cell line model as recruitment of CPSF6 to nuclear speckles had previously been reported following HIV-1 infection in these cells." (PMID 41385587, 2025). "This demonstrates that disruption of CA-CypA binding can modulate the ability of some CPSF6-NLS chimeras to productively support HIV-1 infection." (PMID 39823525, 2025). "In general, the ability of these CPSF6-NLS chimeras to facilitate HIV-1 infection in SupT1 and THP-1 cells was similar to what was observed in HeLa cells." (PMID 39823525, 2025). "CPSF6 also seems to coordinate with other capsid-binding host factors, such as CypA, to orchestrate the early steps of HIV-1 infection." (PMID 40202316, 2025). "In contrast, VSV-G pseudotyped HIV-1 infection rates in CPSF6 knock-out cells were similar to infection rates in NT control cells across all tested conditions." (PMID 41385587, 2025). "These CPSF6 knock-out cells exhibited enhanced permissivity to HIV-1 infection, in line with our previous observations, while knock-out of TRIM5α had no impact on wild-type infection as we previously reported." (PMID 41385587, 2025). "Accordingly, the truncation of the C-terminus of CPSF6 (e.g., a truncation at residue 358, CPSF6-358) leads to the localization of the protein to the cytoplasm and inhibits HIV-1 infection by binding to the capsid and sequestering it from the nucleus." (PMID 39859212, 2025). "This study highlights the magnitude of transcriptional changes that occur in CPSF6 knock-out cells, and these transcriptional changes should be considered when interpreting HIV-1 infection phenotypes in CPSF6 knock-out cells across other cell types." (PMID 41385587, 2025). "Together, these results suggest that CPSF6 plays a role in modulating the innate immune response to HIV-1 infection in CD4+ T cells." (PMID 39678349, 2024). "We observed defective infection for cells expressing the cytoplasmic localizing CPSF6-NLS mutants, while cells expressing the NP and MX2 NLS variants again supported reduced levels of HIV-1 infection." (PMID 38979149, 2024). "Here, we report that CPSF6 knock-out in primary CD4+ T cells leads to increased permissivity to HIV-1 infection due to broad transcriptional reprogramming." (PMID 39678349, 2024). "Taken together, these data suggest that reduced IFN signaling and responsiveness in part explain the enhanced permissivity of CPSF6 knock-out cells to HIV-1 infection." (PMID 39678349, 2024).
HIV-1 infection (continued). "Several additional constructs, including SV40, HNRNP K, and HNRNP A1, supported WT HIV-1 infection levels similar to CPSF6-FL." (PMID 38979149, 2024). "This study highlights the importance of the NLS in CPSF6 in dictating the NPC it associates with and its effect on HIV-1 infection." (PMID 38979149, 2024). "This demonstrates that disruption of CA-cyclophilin binding can modulate the ability of some CPSF6-NLS chimeras productively support HIV-1 infection." (PMID 38979149, 2024). "To further understand if changing CPSF6’s NLS impacts HIV-1 infection, we utilized single-round HIV-1 luciferase reporter virus to infect our chimeric CPSF6 cell lines." (PMID 38979149, 2024). "Taken together, our results show that a subset of our CPSF6-NLS constructs that supported maximal or partial HIV-1 infection nevertheless supported equivalent levels of HIV-1 nuclear entry." (PMID 38979149, 2024). "To track changes in CPSF6 localization following HIV-1 infection, we engineered endogenous monomeric NeonGreen (mNGreen) C-terminal tagged CPSF6 into HT1080 cells (HT1080-CPSF6-mNGreen) via CRISPR-Cas9 knock-in." (PMID 39678349, 2024). "Collectively, our results establish the importance of CPSF6’s NLS in facilitating the intranuclear events of HIV-1 infection." (PMID 38979149, 2024). "Recruitment of CPSF6 to nuclear speckles has been observed during HIV-1 infection, with the extent of colocalization between CPSF6 and nuclear speckles dependent on cell type and timepoint." (PMID 39678349, 2024). "We used HT1080 cells as a cell line model of CPSF6 recruitment to nuclear speckles, as recruitment of CPSF6 to nuclear speckles following HIV-1 infection was observed in 30–40% of infected HT1080 cells in prior studies." (PMID 39678349, 2024). "While CPSF5 knock-out efficiency wasn’t as high as that achieved for CPSF6 as monitored by immunoblot, it still resulted in a significant increase in HIV-1 infection." (PMID 39678349, 2024). "Despite these many roles in the viral lifecycle, reported HIV-1 infection phenotypes upon CPSF6 depletion vary widely by viral strain and cell type, including some conditions that result in an increase in infection." (PMID 39678349, 2024). "Future studies will focus on understanding the viral and host determinants that govern the multifaceted role of CPSF6 in HIV-1 infection." (PMID 39678349, 2024). "Together, these results display the importance of the nuclear import pathway utilized by CPSF6 for productive HIV-1 infection." (PMID 38979149, 2024). "Following HIV-1 infection, CPSF6 relocates from diffuse nuclear staining to discrete puncta that colocalise with SC35-positive nuclear speckles." (PMID 38793552, 2024). "Translocation of CPSF6 to NS induced by HIV-1 infection changes the immunofluorescence microscopy pattern of CPSF6 from diffuse nuclear staining to large CPSF6 condensates or puncta-like structures that are easily recognizable." (PMID 37414787, 2023). "When CPSF6 was first discovered, a deletion mutant of CPSF6 unable to translocate in the nucleus was found as a potent inhibitor of HIV-1 infection." (PMID 36314049, 2023). "The translocation of CPSF6 to NS induced by HIV-1 infection requires an intact capsid since viruses containing capsid mutations such as N74D and A77V fail to induce condensates containing CPSF61,2." (PMID 37414787, 2023). "When we prevented the formation of CPSF6 condensates using a hypertonic medium during infection, wild-type HIV-1 infection was inhibited, but HIV-1 capsid mutants N74D and A77V were much less affected by the hypertonic medium." (PMID 37414787, 2023). "We found that CPSF5, which forms a complex with CPSF6, was present in the condensates suggesting that HIV-1 infection induces the formation of condensates that contain the CPSF52-CPSF62 tetramer." (PMID 37414787, 2023). "Our studies revealed that the accumulation of CPSF6 biomolecular condensates in NS is important for wild-type HIV-1 infection." (PMID 37414787, 2023).
HIV-1 infection (continued). "We and others have previously demonstrated that HIV-1 infection induces the recruitment of CPSF6 to NS1,2,5." (PMID 37414787, 2023). "The addition of the small pharmacological molecules PF74, GS-CA-1, or lenacapavir during infection inhibits translocation of CPSF6 to NS11, and PF74 disassembles CPSF6 condensates preformed by HIV-1 infection." (PMID 37414787, 2023). "CPSF6 in uninfected human cells shows semi-diffuse nuclear labeling, whereas HIV-1 infection triggers the formation of nuclear condensates or puncta structures that contain CPSF6, which colocalize with the NS marker SC35, as previously shown." (PMID 37414787, 2023). "Researchers reported that HIV-1 infection down-regulated miR-125b expression concurrently with the up-regulation of cleavage and CPSF6, which can contribute to promoting HIV-1 nuclear entry and replication." (PMID 36142450, 2022). "Over a decade of research into the roles of CPSF6 in HIV-1 infection has established a battery of powerful virology assays." (PMID 36202818, 2022). "To test the role of CPSF6 in HIV-1 infection of human primary cells, we challenged CPSF6-depleted CD4+ T cells with wild-type and mutant HIV-1." (PMID 35215956, 2022). "Although we previously knocked out CPSF6 from WT and LKO HEK293T cells, creating respective CKO and double knockout DKO cells, we have been unable to similarly knockout CPSF6 from T cell lines commonly used in HIV-1 infection experiments." (PMID 35203306, 2022). "Another target of miR-125b is cleavage and polyadenylation specificity factor 6 (CPSF6), which plays a key role in HIV-1 infection; specifically, during nuclear import and integration targeting." (PMID 36142450, 2022). "These constructs were expressed in CPSF6 KO HEK293T (CKO) cells by gammaretroviral transduction, and various roles of CPSF6 in HIV-1 infection were monitored in the resulting cell lines." (PMID 36202818, 2022). "This difference is responsible for the antiviral effect exerted exclusively by CPSF6-358 that blocks HIV-1 infection by interacting with the capsid core in the cytoplasm and preventing nuclear import." (PMID 33868211, 2021). "Excess cytoplasmic CPSF6 expression inhibits HIV-1 infection, consistent with earlier studies that a truncated cytoplasmic form of CPSF6 restricts HIV-1." (PMID 34835048, 2021). "Our data reveal an interplay between CPSF6 and CypA that is important for cytoplasmic capsid trafficking and HIV-1 infection." (PMID 33758083, 2021). "Cellular depletion of TNPO3 or truncation of the RS domain mislocalized CPSF6 to the cytoplasm and potently restricted HIV-1 infection." (PMID 34154414, 2021). "HIV-1 infection redirects CPSF6 to puncta in nuclear speckles and CPSF6 is responsible for the integration of HIV into active euchromatin in speckle-associated domains (SPADs)." (PMID 34452291, 2021). "We observe that HIV-1 infection induces higher-order CPSF6 formation, and capsid-CPSF6 complexes cotraffic on microtubules." (PMID 33758083, 2021). "CPSF6 was initially identified to be relevant for HIV-1 infection through the functional screening of a mouse cDNA expression library that led to the isolation of a truncated form of CPSF6 (CPSF6-358) inhibiting HIV-1 replication." (PMID 33868211, 2021). "During the normal course of HIV-1 infection, CPSF6 facilitates viral nuclear entry and the targeting of speckle-associated genomic DNA regions for integration." (PMID 34154414, 2021). "CPSF6 was first identified to be relevant for HIV-1 infection through a cDNA library screen in which a truncated form of CPSF6 was found to inhibit HIV-1 replication at the step of nuclear entry." (PMID 31028522, 2019). "In contrast, both CPSF6 knock-down and the N74D exchange impaired HIV-1 infection in post-mitotic primary human macrophages, and this effect was attributed to induction of an interferon response triggered by viral DNA sensing." (PMID 30672737, 2019).